BMAL1 (basic helix-loop-helix ARNT like 1)
Diseases named in the same sentence as BMAL1 in open-access papers (continued):
Sharing a sentence is not in itself a finding about the gene and the disease.
Sepsis (continued). "In sepsis patients, the severity of the inflammatory process is directly related to the degree of change in the clock genes BMAL1 and PER2." (PMID 33900485, 2021). "Recent works showed that conditional deletion of Bmal1 in myeloid cells (Bmal1ΔMye), which disrupt the macrophage clock, accelerated death in sepsis induced by both CLP or LPS and abolished the daily differences in the mortality rate." (PMID 34956930, 2021). "It has been suggested that myeloid-specific Bmal1 deletion disrupts diurnal monocyte trafficking, thereby increasing sepsis-induced systemic inflammation and mortality." (PMID 32396064, 2020). "However, conditional deletion of BMAL1 in myeloid cells, disrupting the macrophage circadian clock, accelerates death in sepsis." (PMID 38938563, 2024). "Levels of Bmal-1 were measured at 2 h after sepsis model building in each ZT time." (PMID 39296207, 2024). "Monitoring rhythmic variables such as Bmal-1 at various points throughout the day during the initial phase of sepsis could facilitate the correlation of Bmal-1 with SICM patient outcomes, which is the concern in further clinical studies." (PMID 39296207, 2024). "During experimental sepsis, Bmal1, the core clock gene, regulates host immune responses." (PMID 39296207, 2024). "The daily variation of sepsis mortality rate is lost in Bmal-1-deficent mice." (PMID 39296207, 2024). "Notably, myeloid-specific Bmal1 deletion disrupts diurnal monocyte trafficking and increases systemic inflammation and mortality in sepsis mouse models." (PMID 32396064, 2020). "In mice, experimental BMAL1 knockout provides a survival advantage in streptococcal pneumonia infection, mediated by improved phagocytic activity and immune cell recruitment, providing experimental evidence that the regulation of clock components has an effect on sepsis responses." (PMID 35880253, 2022). "Thus, a novel insight into the coagulation abnormality in S. oralis infection was gained that may optimize the treatment of sepsis by rescuing the expression of BMAL1 in the liver." (PMID 33042871, 2020). "This led to enhanced STAT1–PD-L1 signalling in the absence of myeloid Bmal1 and an enhanced sepsis phenotype in a cecal ligation puncture model." (PMID 34858390, 2021). "Therefore, it is not surprising to find that Bmal1 is related to pro-inflammatory and anti-inflammatory processes, which are both deregulated during sepsis." (PMID 34956930, 2021). "Previous evidence had shown that mice lacking myeloid Bmal1 displayed heightened PKM2 mediated STAT1 phosphorylation in macrophages, which led to T cell exhaustion and an increase in sepsis and that PKM2 phosphorylates STAT1 to activate macrophages in a model of arthritis." (PMID 34858390, 2021).
sarcopenia (22 papers, 2009 to 2025). Progressive decline in muscle mass due to aging which results in decreased functional capacity of muscles. "Exercise and melatonin were able to restore myogenesis and altered mitochondrial dynamics associated with sarcopenia in Bmal1 KO mice." (PMID 41009036, 2025). "In muscle-specific Bmal1 knock-out mice, which express hallmark features of sarcopenia (circadian and mitochondrial disruption and impaired skeletal muscle function), combined exercise and melatonin treatment reversed these effects independently of Bmal1." (PMID 41009036, 2025). "Overall, results on the causal role of skeletal muscle Bmal1 in age-related sarcopenia thus appear contrasting in mice." (PMID 39747789, 2025). "Animal models suggest that BMAL1 deficiency shortens lifespan, accelerates ageing, and triggers early‐onset sarcopenia." (PMID 38553412, 2024). "BMAL1 deficiency results in muscular atrophy, decreased strength, altered sarcomere organization, and reduced mitochondrial content—key features of sarcopenia." (PMID 38553412, 2024). "The loss of BMAL1 in mice results in reduced lifespan and an acceleration of age-associated phenotypes, including sarcopenia, subcutaneous fat loss, and cataracts." (PMID 37819791, 2023). "It has been shown that the loss of Bmal1 leads to severe aging-associated sarcopenia: The genetic loss of Bmal1 at 9 months of age, resulted in the decrease of about half of the body weight, indicating a premature aging phenotype." (PMID 31484440, 2019). "Whole body Bmal1 knockout in mice causes sarcopenia, i.e., age-dependent reduction of muscle mass, thus muscle loss is not observed in young Bmal1 knockout mice." (PMID 28261043, 2017). "The circadian clock network plays a prominent role in maintenance of skeletal muscle mass, with the loss of Bmal1 leading to severe sarcopenia with age16." (PMID 27540471, 2016). "The first indication that the clock is involved in skeletal muscle maintenance comes from the dramatic phenotype of aging-associated sarcopenia found in Bmal1-null mice." (PMID 27540471, 2016). "A study discovered that Bmal1 deficiency is associated with aging and causes severe sarcopenia." (PMID 38584821, 2024). "Initial characterization of Bmal1−/− mice demonstrated a reduced lifespan and an acceleration in age-associated phenotypes, including sarcopenia, subcutaneous fat loss, and cataracts as well as increased SA-β-gal staining in multiple tissue types suggestive of an increased senescent cell burden." (PMID 37819791, 2023). "Bmal1 knockout mice also show age-associated phenotypes such as body weight loss and sarcopenia." (PMID 28261043, 2017). "Bmal1−/− mice demonstrate the development of multiple age-associated pathologies such as cataracts, sarcopenia, reduced hair growth and progressive atrophy of internal organs: the weight of the spleen, muscles and kidneys is significantly reduced in aged Bmal1−/−mice." (PMID 21149897, 2010). "Indeed, Bmal1 deficiency in preclinical models impairs circadian behavior and accelerates aging, leading to muscle atrophy, reduced strength, disrupted sarcomere organization, and decreased mitochondrial content, all key features of sarcopenia." (PMID 41181393, 2025). "Four papers on mice addressed the role of the core clock gene Bmal1 in age-related sarcopenia either at whole-body level or selectively at the level of skeletal muscles." (PMID 39747789, 2025). "It has been reported that the genetic disruption of core clock genes, including ablation of Bmal1, leads to sarcopenia like phenotypes in mice." (PMID 41321491, 2025). "Bmal1-KO mice also developed age-related decreases in skeletal muscle mass and fiber number and diameter, consistent with the development of sarcopenia." (PMID 39747789, 2025). "Disrupted circadian rhythms, regulated by genes known as BMAL1 and CLOCK, are linked to both LBW and sarcopenia, impacting lipid metabolism, muscle mass, and ageing processes." (PMID 38553412, 2024).
sarcopenia (continued). "Disrupted circadian rhythms, regulated by genes such as BMAL1 and CLOCK, are associated with both LBW and sarcopenia, impacting lipid metabolism, muscle mass, and the ageing process." (PMID 38553412, 2024). "These suggest that the Bmal1 gene is essential for preserving muscle function and structure and for mitochondrial maintenance, thus delaying frailty and sarcopenia." (PMID 38136651, 2023). "When the core component of the circadian clock genes Bmal1 was knocked out, Bmal1−/− mice had reduced lifespan and displayed a number of symptoms of premature aging including sarcopenia, cataracts, less subcutaneous fat, organ shrinkage, and others." (PMID 35563724, 2022). "BMAL1 knockout mice display an early aging phenotype characterized by sarcopenia, decreased hair regrowth, and increased ROS levels in the heart, kidneys, and spleen." (PMID 33889597, 2021). "However, BMAL1’s role in regulating protein turnover appears to be somewhat limited in scope, as it does not play a major role in pathological protein degradation associated with the massively catabolic state of denervation atrophy or in age-associated sarcopenia." (PMID 30096135, 2018). "Notably, muscle-specific deletion of Bmal1 accelerates sarcopenia-like phenotypes by impairing the expression of differentiation factors and altering muscle structure." (PMID 41305621, 2025). "Research indicated that mice with global (whole-body) Bmal1 knockout (KO) exhibited decreased muscle weight, body weight, and lifespan with disrupted circadian rhythms and severe sarcopenia at 40 weeks of age, primarily attributed to reduced muscle fiber diameter and alterations in fiber type." (PMID 40359225, 2025). "Similarly, young adult mice with muscle-specific deletion of Bmal1 exhibited reduced specific force, though premature sarcopenia was initially unreported." (PMID 40324095, 2025). "Muscle growth and homeostasis needs the contribution of muscle satellite cells and their proliferative capacity is constantly reduced with age; the status of sarcopenia observed in Bmal1-null mice could be partially mediated by the decline of the clock function." (PMID 31484440, 2019). "Thus, whether the sarcopenia observed in Bmal1-null mice that resemble early aging could be mediated at least in part by declining clock function in the muscle warrants further investigation." (PMID 27540471, 2016). "Noteworthy, treatment of Bmal1-/- mice with NACcannot completely prevent premature aging; growth retardation, reduced hairregrowth, sarcopenia, and joint ossification were not affected byadministration of NAC." (PMID 20157581, 2009). "However, the causality of the association between the circadian timing system of the liver and sarcopenia variables was not demonstrated, and the effects included both gene upregulation (Per, Cry, Nr1d1, Nr1d2, and Dbp) and downregulation (Bmal1 and Npas2)." (PMID 39747789, 2025). "Therefore, the interaction of the impaired BMAL1 gene, Rev‐Erbα, and LBW may contribute to sarcopenia development." (PMID 38553412, 2024). "However, sarcopenia manifests under free-run (DD) conditions, and mice entirely lacking Bmal1 show severe premature muscle aging, which can be mitigated by Bmal1 reconstitution in both brain and muscle but not muscle alone, likely due to disrupted feeding patterns." (PMID 40324095, 2025).
Infertility (21 papers, 2009 to 2025). "Overall, the existing evidence for implantation related infertility in BMAL1-KO mice can be considered closely associated with the abnormal secretion of reproductive hormones." (PMID 35311235, 2022). "Male circadian mutant mice typically have normal reproductive capacity, although Bmal1 deficiency can cause infertility and clockΔ19 male mice sire smaller litters." (PMID 19172181, 2009). "Loss of Bmal1, a core clock gene, results in behavioral arrhythmicity and infertility." (PMID 35992114, 2022). "Similarly, the analysis of Bmal1 polymorphism rs4757144 in Slovenian and Serbian Caucasian men showed a significant correlation with infertility (P = 0.047), suggesting that clock genes Clock and Bmal1 contribute to successful fertilization." (PMID 27313610, 2016). "As complete loss-of-function mutations in Bmal1 can lead to infertility and are expected to be rare in natural populations, here, we further investigated whether an incomplete loss of Bmal1 function could cause significant autism-like behavioral changes in mice." (PMID 35682995, 2022). "Since systemic Bmal1 knockout (KO) mice have infertility accompanied by decreased progesterone (P4) levels due to decreased ovarian function, serum P4 levels in cKO mice were measured." (PMID 35886985, 2022). "Systemic Bmal1 knockout (KO) female mice were reported to have disorders in multiple organs including multifactorial infertility." (PMID 35886985, 2022). "Previous work has determined that defective progesterone synthesis in the ovary leads to implantation failure, contributing to the infertility of the Bmal1 knockout female." (PMID 35992114, 2022). "We hypothesized that loss of Bmal1 in discrete SCN populations would be sufficient to disrupt circadian rhythmicity and result in infertile females." (PMID 35992114, 2022). "Per1/2-dko mice are fertile and healthy, unlike another commonly used clock-disrupted mouse strain, the Bmal1-ko mouse, that suffers from a variety of health problems (short lifespan, arthropathy, infertility, etc.), and has been used in some other microbiome studies." (PMID 36350921, 2022). "However, ovaries from steroidogenic cell-specific Bmal1 knockouts can continue to produce offspring when transplanted into a wildtype female, suggesting that progesterone production is not the only pathology underlying Bmal1 knockout infertility." (PMID 35992114, 2022). "Targeted ablation of these circadian proteins BMAL1 and CLOCK results in infertility in mice with significant characteristic morphological alterations of CBs which are clearly different from those observed in mice lacking pGRTH (KI) and GRTH null mice." (PMID 33425888, 2020). "It has been shown that infertility or reduced fertility problems showed by Bmal1 KO and Clock KO mice, respectively, are not driven by direct defects in the spermatogenesis." (PMID 22900038, 2012). "Low testosterone and infertility have been reported in mice lacking Bmal1, a core circadian gene also expressed in Leydig cells." (PMID 19172181, 2009). "BMAL1 is significantly elevated ~ 8–10 h after the peri-ovulatory luteinizing hormone (LH) surge at ZT18 on proestrus; female BMAL1 gene knockout mice, however, are infertile likely due to a lack of phasic sensitivity to LH." (PMID 35705939, 2022).
leukemia (21 papers, 2017 to 2025). A malignant (clonal) hematologic disorder, involving hematopoietic stem cells and characterized by the presence of primitive or atypical myeloid or lymphoid cells in the bone marrow and the blood. "Low expression of CLOCK and BMAL1, two key genes associated with the circadian clock, has been observed in leukemias." (PMID 40700255, 2025). "Disruption of the molecular clockwork prompted differentiation with exhaustion of disease-propagating leukemia stem cells and genetic loss of BMAL1 weakened acute myeloid leukemia preservation while normal hematopoiesis was not negatively impacted." (PMID 37620852, 2023). "This interaction holds significant clinical relevance because the expression of clock genes and their proteins, such as CLOCK and BMAL1, has been shown in certain cancers, including leukemia, to acetylate glucocorticoid receptors." (PMID 39518143, 2024). "Deeper analysis of BMAL1 activity, its binding partners and cell type specific expression, in leukemia is warranted." (PMID 38334474, 2024). "One study found that both CLOCK and BMAL1 proteins are required for leukemia stem cell growth, and disruption of the circadian clock leads to LSC differentiation, thereby inhibiting progression." (PMID 38334474, 2024). "Taken together, our data highlight the relevant role played by the core clock genes CLOCK and BMAL1 alongside a proper functioning of the biological clock in the maintenance and progression of leukemia-initiating cells (LICs) in T-ALL." (PMID 37620852, 2023). "Previously published studies reported a leukaemia specific dependency on Bmal1 and Clock in a murine model of acute myeloid leukaemia (AML)." (PMID 36870963, 2023). "In acute myeloid leukaemia, maintenance of circadian homeostasis is required for leukaemia stem cell self-renewal and inhibition of BMAL1 results in the downregulation of β-catenin and other TFs involved in self-renewal." (PMID 31014368, 2019). "CLOCK and BMAL1 are required for acute myeloid leukaemia cell growth and leukaemia stem cell maintenance." (PMID 31014368, 2019). "For example, both leukemia and lymphoma cells have been found to have transcriptionally silenced BMAL1 through promoter CpG island hypermethylation." (PMID 33089179, 2019). "However, Bmal1 has also been reported as an oncogene, such as in acute myeloid leukemia models, where it was shown to be essential for the growth of leukemia stem cell (leukemia stem cell are responsible for disease development and spread)." (PMID 36593479, 2023). "Similarly, targeting Clock or Bmal1 also leads to reduced self-renew capacity and differentiation of murine leukemia stem cells." (PMID 36937362, 2023). "Restoring BMAL1 levels in hypermethylated lymphoma/leukemia cells results in growth inhibition." (PMID 33089179, 2019). "Finally, both Clock and Bmal1 were identified as survival factors for leukemia stem cells, since their genetic (RNAi, CRISPR) or chemical (REV-ERBs agonist SR9011) disruption induces differentiation and growth arrest." (PMID 28425940, 2017). "On the basis of previous evidence that, differently from healthy hematopoietic cells, the leukemia stem cells fully rely on a properly functioning molecular clockwork for survival and growth, we evaluated the role of the core circadian transcription factors BMAL1 and CLOCK in T-ALL biology." (PMID 37620852, 2023). "Therefore, the down-regulation of CLOCK and BMAL1 could be used as a biomarker in leukemia to support the identification of the disease; thus, the elevation of its expression compared to normal levels can be used to follow the response to treatments." (PMID 35897788, 2022). "Strengths of our study include the first report of low‐sucrose diet and timing affecting leukemia progression in a particularly refractory subtype of AML, and being accompanied by an increase in BMAL1 expression." (PMID 38334474, 2024).
leukemia (continued). "PER1/2/3, BMAL1, CLOCK, REV-ERBα, and PPARα were downregulated in all types of leukemia, suggesting their potential role in leukemic development." (PMID 35897788, 2022). "Further, inhibition of Sirt1 causes the “fine-tuning” of circadian gene oscillation for some types of leukemia and in CML patient’s resulting in the complete recovery of BMAL1 oscillation." (PMID 30210557, 2017). "We further assessed if diet timing, regardless of diet modification, can influence leukemia progression and examined BMAL1 protein expression and its pharmacological modulation in AML cell lines." (PMID 38334474, 2024). "As for BMAL1 and CLOCK genes, both were shown to be downregulated in all types of leukemia." (PMID 35897788, 2022). "In a mouse model of acute myeloid leukemia (AML), in vivo RNAi screening identified that the circadian rhythm genes (Bmal1 and Clock) are required for AML cell growth, and targeting the circadian machinery showed therapeutic effects by depleting leukemia stem cells and impaired cell proliferation." (PMID 33816508, 2021). "Surprisingly, healthy cells appear to be resilient to genetic ablation of the circadian clock, as Bmal1 disruption does not produce any gross hematopoietic deficits, thus revealing Bmal1 as an attractive anti-leukemia target." (PMID 28425940, 2017).